IQCF1 (IQ motif containing F1)
Description:
Involved in sperm capacitation and acrosome reaction.
Synonyms: MGC39725
Tractability: No criterion of Open Targets' tractability assessment is met for any kind of drug.
Gene: Protein-coding gene on chromosome 3 (51,894,876 to 51,903,353, reverse strand). Ensembl gene ENSG00000173389.
Subcellular location: Cytoplasmic vesicle, secretory vesicle, acrosome
Gene Ontology:
Molecular function: calmodulin binding
Biological process: positive regulation of acrosome reaction; positive regulation of flagellated sperm motility involved in capacitation
Cellular component: acrosomal vesicle
Genetic constraint (gnomAD): Loss-of-function variants: 11 observed, 11.88 expected, observed/expected ratio (o/e) 0.93, 90% interval 0.58 to 1.52. The synonymous counts are far from expectation, so gnomAD's model fits this gene poorly and the ratio says little. Missense variants: 252 observed, 266.3 expected, observed/expected ratio (o/e) 0.95, 90% interval 0.85 to 1.05. Synonymous variants: 67 observed, 101.55 expected, observed/expected ratio (o/e) 0.66, 90% interval 0.54 to 0.81.
Homologues: Orthologues: chimpanzee IQCF1 (98% identical), macaque IQCF1 (94% identical), pig IQCF1 (61% identical), dog IQCF1 (61% identical), rat Iqcf1 (52% identical), mouse Iqcf1 (51% identical). Paralogues in human: IQCF5 (42% identical), IQCF2 (35% identical), IQCF6 (29% identical), IQCF3 (26% identical).